FASN (fatty acid synthase)
Diseases named in the same sentence as FASN in open-access papers (continued):
Sharing a sentence is not in itself a finding about the gene and the disease.
cancer (continued). "The effects of metformin on energy homeostasis in normal and cancer cells have been characterized by the blocked activation or expression of key fatty acid biosynthesis enzymes (e.g., ACC, FASN, HMGCR) and enhanced expression of regulators of mitochondrial biogenesis (e.g., PCG-1α)." (PMID 22203527, 2011). "However, as recently reported by Terry A.R., HCC patients are not included in the six ongoing clinical trials for FASN inhibition in cancer." (PMID 40507339, 2025). "By inhibiting FASN, the enzyme in lipid metabolism responsible for synthesizing palmitate from acetyl-CoA and malonyl-CoA using NADPH, combined with standard treatments might significantly weaken cancer cells." (PMID 39329757, 2024). "The down-regulation of FASN during IC2-stimulated LD formation suggests that FA synthesis may not be necessary for the formation of LDs in the cancer cells." (PMID 39725994, 2024). "Moreover, IC2-stimulated LD formation did not depend on de novo FA synthesis in the cancer cells, as inhibition of FASN did not reduce LD formation." (PMID 39725994, 2024). "In addition, leptin decreases FASN and increases FAO in MCF-7 breast cancer cells, suggesting that leptin-mediated changes in lipid metabolism may support cancer progression." (PMID 39609706, 2024). "Thus, they assessed the expression level of fatty acid synthase (FASN) and their function in a preclinical model of HER2+ GC and evaluated the inhibition of FASN impacting on resistance to anti-HER2 treatment in HER2+ GC, especially when targeting HER2+ cancer stem cells (CSCs)." (PMID 39409942, 2024). "Unlike most adult organs, high levels of FASN characterize the developing embryo and cancer cells." (PMID 39064589, 2024). "In contrast to the off-target effects reported with many anticancer drugs that target genes required for cancer proliferation in a cell-autonomous manner, we previously found that the efficacy of the FASNi TVB-3166 was largely prevented by CRISPR/Cas9-driven FASN KO." (PMID 39349429, 2024). "As lipid metabolism differs between cancer cells and normal cells, the effects of FASN on oxidative effects in the mitochondria may not be the same in A549 cells and normal cells." (PMID 37270622, 2023). "All three enzyme families involved in FA synthesis (ACC, FASN, SCD) are frequently up-regulated in several cancer types, including glioblastoma, breast, ovarian, lung, prostate and liver cancer; furthermore, their expression correlates with poorer prognosis and high cancer grade." (PMID 36839759, 2023). "The overexpression of fatty acid synthase (FASN) gives cancer cells a proliferative advantage; conversely, lipolysis, through the activation of lipoprotein lipase (LPL), could increase the availability of FAs to levels necessary for cancer cell proliferation." (PMID 36983080, 2023). "Additionally, the ImmuCellAI results revealed a strong negative correlation between FASN expression and the infiltration scores in 18 cancer types across 33 cancer types." (PMID 36555243, 2022). "In addition, we investigated the relationship between FASN and immune checkpoint gene expression and found that FASN was significantly positively correlated with the immune checkpoint genes CD276 and VEGFA in as many as 27 cancer species." (PMID 36555243, 2022). "In this section, we showed that FASN could modulate PDGF-AA and IGFBP-3 secretion to affect lymphangiogenesis, which will hopefully lead to the identification of more messengers in the communication between cancer cells and HLECs." (PMID 35597782, 2022). "We speculated whether FASN exhibited negative correlations in multiple cancer types directly by affecting the transcription factors shared by these MHC molecules." (PMID 36555243, 2022).
cancer (continued). "Many types of cancers that have lost PTEN depend more on lipid metabolism than on anaerobic glycolysis, and for this reason, silenced PTEN is capable of activating the transcriptional factor SREBP, leading to an overexpression of fatty acid synthase, and in the same manner, their β-oxidation." (PMID 35745875, 2022). "Additional studies have demonstrated that FASN catalyzes formation of long-chain fatty acids from acetyl coenzyme A, malonyl coenzyme A and NADPH, to promote proliferation of VCaP cells, and that inhibition of FASN effectively and selectively kills cancer cells." (PMID 35747825, 2022). "Due to cerulenin’s ability to inhibit fatty acid synthase (FAS) that, in turn, decreases the expression of ErbB1, 2, and 4, it may initiate an epithelial-to-mesenchymal transition (EMT) as well as the migration and invasive ability of cancer cells." (PMID 34944904, 2021). "In addition, in biologically aggressive human tumors, overexpressed USP2a interacts with and stabilizes fatty acid synthase (FAS), which is now recognized as a potentially therapeutic target in cancers of the breast, colon, endometrium, ovary, prostate, and thyroid." (PMID 34956872, 2021). "In this study, we hypothesized that the compensatory adaptive response of lipid metabolism by FASN inhibitors in cancer cells can be counteracted by reducing FASN levels using IU1, a USP14 inhibitor, and therefore inhibiting FASN and USP14 together will dramatically suppress the cancer cell growth." (PMID 34948233, 2021). "Moreover, various enzymes involved in de novo lipogenesis pathway are significantly up-regulated in cancers, such as acetyl-CoA carboxylase (ACC) and fatty acid synthase (FASN) in FA synthesis and 3-hydroxy-3-methylglutaryl-CoA reductase (HMGCR) in cholesterol synthesis." (PMID 34888248, 2021). "Whilst hesperidin, but not sesame extract, in MSO exhibited cancer chemopreventive efficacy, both of them could reduce lipid accumulation by suppression of FASN expression." (PMID 34683980, 2021). "Moreover, it is shown that FASN overexpression may inhibit TNF‐α expression, caspase 8 and NF‐κB activation in several cancer cells." (PMID 33939282, 2021). "Notwithstanding the fact that several inhibitors of FASN, including C75, cerulenin, and orlistat, have shown high efficacies in selective targeting of cancer cells, they have not been translated into clinics because of the severe side effects and toxicity they have caused to normal tissues." (PMID 33673109, 2021). "Hence, we hypothesized that the regulation of FASN levels by USP14 is a minor indirect effect and that the regulation of cancer proliferation by USP14 is through a pathway other than the FASN-controlled de novo lipogenesis pathway." (PMID 34948233, 2021). "Therefore, we conclude that USP14 inhibition does not compensate for the weakness of the FASN inhibitor and suggest that the use of both inhibitors together as cancer therapeutics is undesirable." (PMID 34948233, 2021). "Indeed, treatment of an USP14 inhibitor IU1 did not significantly affect FASN levels in cancer cells." (PMID 34948233, 2021). "The association between the expression of FASN and FOXA1 in cancer has not been examined." (PMID 32103349, 2020). "In cancer cell lines, the mTORC1 signal can also promote de novo lipid synthesis through the sterol responsive element-binding protein (SREBP) transcription factors, which induce the expression of metabolic genes responsible for lipid biosynthesis, including fatty acid synthase (FASN)." (PMID 33511116, 2020).
cancer (continued). "Furthermore, pharmacological inhibition of FASN has been shown to be lethal to cancer cells in vitro and in vivo but not to normal cells, highlighting the importance of FAs in cancer biology while simultaneously revealing a promising therapeutic window." (PMID 32226926, 2020). "Last but not least, FASN was reported to be relating to cancer cell apoptosis." (PMID 30931932, 2019). "Furthermore, FASN promotes EMT in ovarian, breast, and colorectal cancers." (PMID 29385093, 2018). "In accordance with this view, we observed a reduction in FASN levels, which could limit the initial step in FA biosynthesis, and the KEGG indication of an increase in lipid degradation, suggesting that cancer cells scavenge lipids from the extracellular environment." (PMID 29615075, 2018). "BCSCs (CD24− CD44+ ESA+) isolated from MCF10DCIS.com cells, which give rise to ductal carcinoma in situ, exhibit higher expression levels of lipogenic genes such as ATP citrate lyase (ACLY), acetyl CoA carboxylase 1 (ACC1), and FASN compared to non-stem cancer cells." (PMID 29907133, 2018). "Moreover, C75 treatment abrogated acetate-induced cancer cell survival without affecting FASN and ACACA mRNA levels." (PMID 27357947, 2016). "Indeed, a fatty acid synthase (FASN)- driven “lipogenic state”, by conferring growth and survival advantages, and cross-talking with established cancer-controlling signaling pathways, appears to necessarily accompany the natural history of most human cancers." (PMID 27713913, 2016). "As both enzymes are molecular targets for cancer therapy, with specific inhibitors of FASN activity or by inducing LPL activity in non-cancer tissues by peroxisome proliferator-activated receptor γ agonists, PEMT may also be a promising diagnostic and therapeutic target." (PMID 24932311, 2014). "However, the mechanism explaining how deprivation of FASN expression and fatty acid synthesis contribute to apoptosis in cancer cells is still not clear." (PMID 25255125, 2014). "The levels of ACLY mRNA in cancer and non-cancer tissues were determined as 104.4±100.9 and 104.9±100.6 copies/μg total RNA, respectively, while the levels of FASN mRNA in cancer and non-cancer tissues were determined as 104.8±100.8 and 105.1±100.5 copies/μg total RNA, respectively." (PMID 24649254, 2013). "An increased FASN expression renders cancer cells no longer responsive to the nutritional cue." (PMID 23725225, 2013). "However, IPI-9119 does not exert significant antiproliferative effects on various tumor cell lines in vitro, suggesting that inhibiting FASN alone may not be sufficient to impact cancer cell proliferation and tumor growth." (PMID 41421797, 2025). "Consequently, several enzymes involved in LD formation or breakdown, such as ACC, fatty acid synthase (FASN), 3-hydroxy-3-methylglutaryl monoacyl-CoA reductase (HMGCR), and stearoyl-CoA desaturase (SCD), have been identified as potential therapeutic targets in cancer treatment." (PMID 38916672, 2024). "In addition, interestingly, lipogenic genes, including SREBFs, ACLY and FASN, were reduced by LPIN1 knockdown, suggesting that LPIN1 is not a passive lipogenic gene but a driver gene that actively induces alterations in lipid metabolism in TKI-resistant cancer cells." (PMID 35565351, 2022). "In addition, inhibition of FASN (fatty acid synthase) can increase the expression of CD36 in cells, thereby increasing the proliferation of CRC cells, suggesting that the combination of inhibition of CD36 and increase of FASN expression can further increase the anti-cancer effect." (PMID 37305350, 2022). "However, a systematic analysis of fatty acid synthase across pan-cancers has not been carried out." (PMID 34879004, 2021). "However, there are still no effective FASN inhibitors for cancer treatment." (PMID 30824767, 2019).
cancer (continued). "Inhibition of key enzymes in the DNL pathway, namely, ATP citrate lyase, acetyl-CoA carboxylase, and fatty acid synthase (FASN) can increase apoptosis without cytotoxicity to non-cancerous cells, leading to the search for and presentation of novel selective and powerful targets for cancer therapy." (PMID 29588626, 2018). "In addition, GA inhibited the de novo lipogenesis of cancer cells through inducing activation of AMP-activated protein kinase (AMPK) signaling and downregulated the expression of key enzymes (e.g. acetyl-CoA carboxylase [ACC], fatty acid synthase [FASN]) involved in lipogenesis." (PMID 25895130, 2015). "Therefore, we wanted to determine whether GA-induced reduction of lipid drops in cancer cells is mediated by regulating expression of key lipogenic genes, e.g., acetyl-CoA carboxylase (ACC), fatty acid synthase (FASN), sterol regulatory element binding transcription protein (SREBP)-1, and SREBP-2." (PMID 25895130, 2015). "Furthermore, even though there is clear evidence that the energy status of tumor cells is crucial for maintenance of the transformed phenotype and metastatic capabilities, the role of FASN in the regulation of energy homeostasis in cancer cells is not yet established." (PMID 25970773, 2015). "The lipogenic gene Fatty Acid Synthase (FASN) is a significant therapeutic target, given its key role in mediating the synthesis of new FAs in most cancer cells, whereas most noncancer cells preferentially utilize exogenous FAs." (PMID 40137165, 2025). "Cancer cells from both ER+HER2+ and ER+HER2- MBC samples showed higher expression of FASN than FBC samples, independent of HER2 status." (PMID 37696831, 2023). "In cancer cells, EGCG was reported to reduce FASN activity and free fatty acid levels without affecting protein expression." (PMID 35243817, 2022). "Meanwhile, these genes regulated by SREBP-1, including ACLY, ACC, FASN, and SCD, are highly expressed in cancer tissues compared to adjacent non-tumor tissues, which play essential roles in the growth, metastasis, and survival of various cancers." (PMID 35912181, 2022). "Another example of using the not obvious drug for cancer treatment can be NPs loaded with orlistat, which is the FDA-approved anti-obesity drug with the ability to block the lipogenic activity of fatty acid synthase (FAS) present in 50% of cancer cells." (PMID 33802531, 2021). "Taken together, the results reveal that USP14 negatively regulates FASN levels unexpectedly in the cancer cells, and as a result, inhibition of USP14 was not conducive to cancer cell death through inhibition of FASN." (PMID 34948233, 2021). "Interdependence of AR and FASN drives AR-dependent CRPC progression, but overexpression of FASN is the rule rather than the exception in many types of cancers." (PMID 33163409, 2020). "G9P infection was found to downregulate the expression of ACSL4 (acyl-CoA synthetase long chain family member 4), a gene involved in inflammation, cell death, female fertility, and cancer regulation, and FASN (fatty acid synthase regulating virus entry, host IFN response) (data not shown)." (PMID 37515094, 2023). "Although FASN inhibitors, including C75, C93, GSK837149A, Orlistat and TVB-3166, have demonstrated preclinical antitumor activity in cancer cell lines and xenograft models, none of these compounds have been tested in cancer patients due to side effects." (PMID 35898882, 2022). "However, inhibition of both FASN and USP14 had no significant synergistic effect on cancer cell proliferation and, surprisingly, it was confirmed that USP14 negatively regulates the protein level and activity of FASN in cancer cells." (PMID 34948233, 2021). "However, when FASN and USP14 were inhibited together, there were no synergistic effects on cancer cell death compared to inhibition of FASN alone." (PMID 34948233, 2021).
cancer (continued). "Indeed, pharmacological approaches to increase FAO are available, mainly through the use of peroxisome proliferator-activated receptor PPAR agonists or fatty acid synthase FASN inhibitors but are not explored yet in cancer." (PMID 32923440, 2020). "Because endogenous FASN is not required in most adult tissues and due to the specificity of the IDH1-dependent reductive carboxylation process in cancer cells, this mechanism is a highly attractive, cancer-specific target." (PMID 31676791, 2019). "Consequently, we demonstrate that USP14 regulates proliferation of the cancer cells in a fatty acid synthase-independent manner, and targeting USP14 in combination with FASN may not be a viable method for effective cancer treatment." (PMID 34948233, 2021). "Although TVB-3166 has been shown to sensitize cancer cells to chemotherapy, the radiosensitizing efficacy of TVB-3166 has not previously been evaluated, and it appears from the current study that this FASN inhibitor does not radiosensitize in a similar manner to C75." (PMID 33083663, 2020). "Indeed, all the CATs-treated FASN+ HAP1 populations reached a long-term equilibrium at CIs between 0.5 and 1 that may reflect the limited capacity of CATs to kill all the target FASN+ cancer cells regardless of the E:T ratio employed." (PMID 39349429, 2024). "Moreover, previous reports have indicated that FASN serves as a substrate for USP14 in hepatocytes, but other reports suggest that FASN levels in cancer cells are not considerably impacted by the USP14 inhibitor IU1, suggesting that FASN may not be a direct substrate of USP14 in cancer cells." (PMID 39048965, 2024).